NOTCH4 (notch receptor 4)
Diseases named in the same sentence as NOTCH4 in open-access papers (continued):
Sharing a sentence is not in itself a finding about the gene and the disease.
tumor (continued). "The risk score was calculated as follows: risk score = 3.13 × (Notch4) ± 1.52 × (p-PKCα/β2) + 0.74 × (XIAP) + 0.58 × (CDK2) + 0.77 × (Akt1) + 0.74 × (TNM stage) + 1.20 × (vascular/lymphatic invasion) + 0.97 × (tumor size) + 0.61 × (age) + 0.58 × (histologic differentiation)." (PMID 31399040, 2019). "For example, Notch4 intracellular domain when expressed under the control of the whey acidic promoter (WAP) or Notch1, Notch3, or Notch4 intracellular domains under the control of the mouse mammary tumour virus (MMTV) promoter all cause tumour formation in mice." (PMID 26880941, 2016). "We found that protein expression was upregulated in 43.57%, 45%, 56.31%, and 42.71% of tumor tissue in Notch1, Notch2, Notch3, and Notch4, respectively." (PMID 41027955, 2025). "The therapeutic potential of anti-Notch4 antibodies in tumor treatment has been demonstrated in murine model of breast cancer." (PMID 40851037, 2025). "They showed that downregulation of Notch4 hampered VM network formation and hindered cell migration and invasion in vitro and tumor growth in vivo." (PMID 39766289, 2024). "Exploring Notch-specific targets such as NOTCH3-targeted antibody drug conjugates and/or NOTCH4 monoclonal antibodies can help determine if there is greater tumor response and less toxicity with more specific targeted therapy in uLMS." (PMID 38927890, 2024). "To examine the role and therapeutic potential of Notch4 in tumor angiogenesis, we developed a first-in-class therapeutic blocking antibody against Notch4." (PMID 38984877, 2024). "Although both Notch1 and Notch4 are highly expressed on tumor ECs, only the effects of Notch1 signal inhibition have been intensively studied." (PMID 38984877, 2024). "To correlate the translatomic signature of tumor ECs with phenotypic changes in response to anti-Notch4 treatment, we assessed vascular growth and functional perfusion." (PMID 38984877, 2024). "Treatment with 6-3-A6 or E7011 substantially reduced tumor growth and vessel function in multiple murine cancer models in which Notch4 was expressed in the tumor endothelium." (PMID 38984877, 2024). "We conclude that targeting Notch4 improves tumor growth control through endothelial intrinsic mechanisms." (PMID 38984877, 2024). "Based on the close relationship between NOTCH4 and tumor metastasis, we verify the relationship between NOTCH4 and metastasis of GC firstly." (PMID 39309008, 2024). "In our study, the direct effects of Notch4 blockade on tumor vasculature via E7011/6-3-A6 treatment varied depending on the stage of tumor growth." (PMID 38984877, 2024). "We provide compelling evidence that endothelial Notch4 promotes cancer development and alters the tumor vasculature." (PMID 38984877, 2024). "Notch 2 was also identified at the level of hepatocellular carcinoma metastases, while Notch 4 promoted tumor aggressiveness and metastasis." (PMID 38927059, 2024). "To evaluate the function of tumoral Notch4, we first determined tumor cell and stromal cell types that express Notch4." (PMID 38984877, 2024). "We conclude that the development of a first-in-class mAb, E7011/6-3-A6, which specifically blocks Notch4 activity, provides a major therapeutic advance against tumor growth." (PMID 38984877, 2024). "The ability of E7011 to reduce vessel perfusion was observed at all dosages tested, down to 1 mg/kg, demonstrating that Notch4 blockade efficiently disrupts tumor vessel function." (PMID 38984877, 2024). "Notch4 was expressed in tumor endothelial cells in multiple cancer models, and endothelial expression was associated with response to E7011/6-3-A6." (PMID 38984877, 2024). "Enhanced tumor inhibition occurred when anti-Notch4 treatment was used in combination with chemotherapeutics." (PMID 38984877, 2024). "In summary, we have generated a first-in-class antibody against Notch4 and documented the ability of Notch4 blockade to inhibit tumor growth." (PMID 38984877, 2024).
tumor (continued). "Prior studies have indicated that Notch4 can be expressed by tumor endothelium, immune cells, and some cancer cells." (PMID 38984877, 2024). "Many tumor-cell characteristics, including stem-like self-renewal, EMT, radio- and chemo-resistance, and angiogenesis, have been linked to NOTCH4, and most research suggested that NOTCH4 is abnormally overexpressed during cancer development." (PMID 38186223, 2024). "We developed highly specific Notch4-blocking antibodies, 6-3-A6 and humanized E7011, allowing therapeutic targeting of Notch4 to be assessed in tumor models." (PMID 38984877, 2024). "Our findings using different tumor models indicated that endothelial Notch4 in tumor vasculature was critical for 6-3-A6/E7011 to restrict tumor growth." (PMID 38984877, 2024). "The high expression of Notch4 was clearly correlated with the histological grade of the tumour (p < 0.001), PCNA immunohistochemical expression (p < 0.001), depth of invasion (p < 0.001) and angioinvasion (p < 0.001)." (PMID 37108670, 2023). "Notch4 protein expression was found to be high in 6 (24.00%), 58 (87.88%), and 37 (97.37%) of G1, G2, and G3 tumours, respectively." (PMID 37108670, 2023). "The level of Notch4 expression was found to be significantly related to the histological grade of the tumour (p < 0.001, Chi2 test)." (PMID 37108670, 2023). "We analyzed activated levels in tumor cells from EGFR-driven LUAD and found that only the activated form of NOTCH4 (NICD4) was greatly increased in tumor samples resistant to EGFR TKIs compared with those sensitive to EGFR TKIs." (PMID 37268635, 2023). "Our work is also the first to show the localisation of Notch4 in tumour tissue at the electron microscopic level by using the immunogold labelling method and confocal fluorescence microscope." (PMID 37108670, 2023). "As a member of the NOTCH family, NOTCH4 has been amply demonstrated to participate in tumor invasion, differentiation, proliferation, and apoptosis in a spectrum of different tumor cells." (PMID 37190201, 2023). "Notch4 is expressed in tumor cells, and it affects tumor invasion, metastasis, and patient prognosis." (PMID 37765264, 2023). "For instance, patients with NOTCH4 mutations exhibited higher TMB, TNB, and numbers of DDR pathway mutations, compared with patients with wildtype tumors, indicating increased tumor immunogenicity." (PMID 35967450, 2022). "An increase in Notch4 expression has been correlated with migratory, invasive, and tumor-like properties of cells." (PMID 35563241, 2022). "We found that the “Notch4-GATA-IRG” set of genes were over-expressed in tumor tissue by the same magnitude in LOCRC [fold change 1.09 (95% CI 1.07–1.12)] and in EOCRC [fold change 1.08 (95% CI 1.06–1.12)] (ANOVA interaction p = 0.71)." (PMID 36430738, 2022). "Although most Notch4-related studies suggest that Notch4 signaling activation is oncogenic, a Notch4-induced tumor suppressor mechanism has also been identified." (PMID 35945960, 2022). "Previous literature has described that notch-1 and 2 act as oncogenic agents, while notch-4 functions as a tumor suppressor." (PMID 35815090, 2022). "We have identified a novel role for Notch4 signaling with tumor-promoting function in pancreatic tumorigenesis." (PMID 36970723, 2022). "Profoundly, global inactivation of Notch4 led to improved overall survival and reduced tumor burden of the N4−/−PKC comparing with the PKC mice." (PMID 36970723, 2022). "Above all, these results demonstrate that silencing of Notch4 inhibits tumor progression and metastasis of LUAD cells in vivo." (PMID 34988077, 2021). "The expression of ADAM10, Notch1, Notch2, Notch3, Notch4, Hey1, vimentin and N‐cadherin at the transcript level was significantly upregulated, whereas transcripts of E‐cadherin significantly decreased in tumour tissues versus in normal liver tissues of HCC." (PMID 33955149, 2021).
tumor (continued). "BCSCs ectopically expressing Notch 4 in TNBC have shown increased proliferation and invasiveness, whereas inhibition/knockdown of Notch4 decreases cell proliferation, invasion, tumor volume, and tumorigenicity." (PMID 34944829, 2021). "Targeting the DLL3/Notch4 axis instead allowed to affect tumor-derived endothelial cells and neoplastic angiogenesis upregulated under doxorubicin therapy by reducing Notch4-driven transcription of VEGFR3." (PMID 34680255, 2021). "We further assessed Notch4 expression in A549 and H1299 cells exposed to hypoxia for different times given the central role of hypoxia in the regulation of tumor progression." (PMID 34988077, 2021). "An overexpression of Notch1 and Notch4 can also be found in iCC and eCC, correlating with tumor aggressiveness." (PMID 33498866, 2021). "For instance, studies show that Notch receptors such as Notch1 are overexpressed in PDAC, with in vitro studies pointing at a reduction of tumor-promoting factors by e.g., Notch4 inhibition." (PMID 33498866, 2021). "At the same time, a comparison of activated Notch receptors in CSCs and tumor-initiating mammary cells showed that Notch4 is activated in TNBC CSCs." (PMID 34771512, 2021). "TNBC cells ectopically expressing Notch4 showed increased proliferation and invasiveness, while inhibition/knockdown of Notch4 decreased cell proliferation, invasion, tumor volume, and tumorigenicity." (PMID 34771512, 2021). "For PDAC, the expression of ADAM17 (p = 0.008, IHC-score 3.43 vs. 1.73), CD44 (p = 0.012, IHC-score 3.64 vs. 2.27), Notch1 (p = 0.012, IHC-score 2.21 vs. 0.64), and Notch4 (p = 0.008, IHC-score 2.86 vs. 0.91) was significantly higher in the tumor tissue." (PMID 33498866, 2021). "Following the knockdown of Notch 4 or Notch 1, the more efficient inhibition of mammosphere formation in vitro and tumour initiation in vivo was observed in the Notch 4 knockdown model; results representative of the effects on BCSCs." (PMID 32575680, 2020). "This is illustrated for example by studies on tumor initiation (Notch1; Notch3), stem cell control (Notch1; Notch4; Jag1; Jag2; DLL1), angiogenesis (Notch1; DLL4) invasion and metastasis in remote organs (Notch1; Notch2; Jag1; DLL1)." (PMID 32605277, 2020). "The NOTCH4+ BCSCs were highly potential in tumor initiation and were characterized by enhanced invasion and chemoresistance ability." (PMID 32104513, 2020). "To further demonstrate that the NOTCH4+ subpopulation enriched CSCs in vivo, we performed serial dilution tumor transplantation using SUM149 to assess the CSC frequency of the sorted NOTCH4-, NOTCH4+, and total populations." (PMID 32104513, 2020). "Further research demonstrated that Notch1 and Notch4 immunoreactivity significantly correlated with tumor grade and Ki67 expression in triple-negative breast tumors." (PMID 33003540, 2020). "Further, the densitometric analysis of the blots confirmed that Notch4 was significantly downregulated in OVC suggesting its importance in the prognosis of the tumor subtypes." (PMID 29162408, 2019). "The authors state that Notch4 promoted tumor growth and metastasis through the finding of Notch4 nuclear localization in both primary tumors and lung metastasis." (PMID 31379945, 2019). "All together these results suggest that high Notch4 levels are crucial to promote mesenchymal signature and to keep pro-stemness signaling constant during tumor progression of TNBC." (PMID 31379945, 2019). "In accordance with these findings, the expression of Notch4 correlated with overall poor prognosis and experimental evidence indicates that Notch4 contributed to tumor invasion and metastasis by sustaining EMT at the invasive front of primary tumors." (PMID 31379945, 2019). "In TNBCs, the inhibition of Notch-4 significantly reduced Notch-4 dependent proliferation and invasiveness, leading to marked reduction in tumor volume and tumorigenicity." (PMID 30248941, 2018).
tumor (continued). "We also tried to visualize the vascular shunts present in tumors as an exploratory study with a NOTCH4 overexpression tumor xenograft model." (PMID 28862627, 2017). "Several evidence reported that in vivo hypoxia upregulated expression of Dll4, Jagged1, Notch1, Notch4, Hes1, and Hey which in turn promoted tumor angiogenesis." (PMID 28157712, 2017). "NOTCH4 is part of the NOTCH signalling pathway which has been widely implicated in cancer and shown to act as both oncogene or tumour suppressor depending on the context." (PMID 28650955, 2017). "Notch1, Notch2 and Notch4 mRNA expression levels were similar in AtT20 cells and normal adult pituitaries whereas Notch3 mRNA expression was reduced in corticotrope tumor cells in relation to normal mouse pituitary cells." (PMID 28915655, 2017). "When comparing lean and obese in the type I tumor only, significantly higher expression in Notch1, Notch4, DLL4, OB-R, and IL-1R tI were found in obese patients (p < 0.05)." (PMID 28659656, 2017). "WB analyses of pooled tumor lysates showed that PC xenografts derived from leptin treated-tumorspheres had significantly higher levels of Notch4, DLL4, JAG1, survivin, PCNA and Oct-4." (PMID 27999190, 2017). "Having previously established that endothelial Jagged1 is able to activate Notch4 in a physiological angiogenic response, we wanted to confirm this in a tumor setting." (PMID 26213336, 2015). "In the majority of the tumor cell line types, mutations were found in at least three different Notch receptor genes, but with liver as a notable exception, where only NOTCH1 and NOTCH4 were found to be mutated." (PMID 25907971, 2015). "Overall, these data suggest that BCSCs, measured by tumor-initiating activity and enriched by short-term anti-estrogen treatments, are dependent on NOTCH4 signaling that can be blocked by combination treatment with a NOTCH4 inhibitor." (PMID 26387946, 2015). "More importantly, we discovered that Notch4 immuno-reactivity was increased in vessels of the tumor (vii-xii) relative to that in normal mouse mammary glands (i-vi)." (PMID 23601498, 2013). "To confirm that vessel density is similar between tumors developed in wild type and Notch4−/− hosts, we quantified vessel segments at 14 days after transplantation when tumor incidence is still significantly reduced." (PMID 23601498, 2013). "We found increased Notch4 expression specifically in the tumor vasculature relative to blood vessels in the adjacent normal tissue." (PMID 23601498, 2013). "We demonstrate a contribution of the tumor microenvironment, namely the host Notch4, to tumorigenesis." (PMID 23601498, 2013). "Tumor-bearing wild type and Notch4−/− mice were dissected three weeks after transplantation, when tumor incidence is comparable between the two host genotypes." (PMID 23601498, 2013). "One week after transplantation, tumor incidence was 27% in wild type hosts, but only 7% in Notch4−/− hosts, and two weeks after transplantation, tumor incidence was still significantly reduced in the Notch4−/− hosts." (PMID 23601498, 2013). "We found that tumor onset was significantly delayed in Notch4−/− hosts compared to wild type controls." (PMID 23601498, 2013). "Given that Notch4 is predominantly expressed in the normal endothelium and upregulated in the tumor vasculature, we examined blood vessels of tumors transplanted into wild type and Notch4−/− mice." (PMID 23601498, 2013). "The transcriptional orientation of the MMTV genome relative to the transcriptional orientation of the gene in which it integrated, was determined for four genes (Usp31, Nckap5, Cadm2 and Notch4) for which there was available tumor RNA." (PMID 23131872, 2012). "In primary oncosphere-derived tumors we observed enhanced Mmp10 and Notch4 staining at the interface between the tumor and surrounding tissue, suggesting a role for Mmp10+/Notch4+ cells in tumor invasion." (PMID 22545096, 2012).
tumor (continued). "Notch4 staining exhibited a similar pattern, indicating co-expression of Mmp10 and Notch4 in tumor cells at the interface of the tumor and surrounding stroma (upper)." (PMID 22545096, 2012). "In contrast, tumor cells isolated from orthotopic tumors consisted of ∼11% CD133+/Notch4+ cells, consistent with parental CMT167 cells." (PMID 22545096, 2012). "Additional Notch receptor-specific reagents or new conditional genetic mouse models will be instrumental for delineating the relative contribution of Notch1 and Notch4 to tumor angiogenesis." (PMID 21923938, 2011). "We have previously reported that tumour sinusoidal ECs change their phenotype and express the active form of Notch4, an arterial EC marker." (PMID 21528105, 2010). "We have previously reported that the VEGF-A/Dll4/active Notch4/ephrine B2 cascade promotes liver vessel anomalies in HCC and that Notch4 is only expressed in tumour sinusoidal ECs." (PMID 21528105, 2010). "Notch1 and Notch2 were undetectable, whereas Notch4 was noted in limited number of tumor cells." (PMID 39548190, 2025). "Additional translatomic analysis at various timepoints during tumor progression and single-cell RNA sequencing analysis may be needed to better understand endothelial and tumor microenvironmental influences of Notch4 on tumor growth." (PMID 38984877, 2024). "MMTV-PyMT–derived tumors implanted in Notch4-knockout mice exhibited reduced vessel perfusion and delayed onset of tumor growth, suggesting that Notch4 plays a distinct role in tumor endothelial function, although final tumor growth was not affected in this model." (PMID 38984877, 2024). "The precise nature of the signals by which endothelial Notch4 regulates tumor endothelial function remains unclear." (PMID 38984877, 2024). "Whether changes in hypoxia are also involved in Notch4-mediated tumor inhibition remains to be explored." (PMID 38984877, 2024). "Moreover, the results suggest that Notch4 function and signaling differ substantially from those of Notch1, which suppresses tumor angiogenesis and activates canonical signaling." (PMID 38984877, 2024). "As seen in the xenograft models, endothelial Notch4 expression varied among tumor types." (PMID 38984877, 2024). "Notch4 inhibition affected tumor growth, tumor vessel function, and perfusion." (PMID 38984877, 2024). "Our results show that targeting Notch4 specifically alters perfusion and vessel area, contributing to improved tumor control in single or combination therapy; thus, these novel Notch4-blocking antibodies represent a powerful new tool for altering the tumor vasculature." (PMID 38984877, 2024). "Another outstanding question relates to how Notch1 and Notch4 signaling overlaps in tumor ECs." (PMID 38984877, 2024). "Interestingly, the strong expression of Notch4 protein was noted in 24% of G1 tumours, 88% of G2 tumours and 97% of G3 tumours." (PMID 37108670, 2023). "High Notch4 expression was markedly correlated with the histological grade of the tumour (p < 0.001, Chi2 test), depth of invasion (p < 0.001, Chi2Yatesa test), angioinvasion ((p < 0.001, Chi2Yatesa test) and PCNA immunohistochemical expression (p < 0.001, Chi2Yatesa test)." (PMID 37108670, 2023). "Furthermore, by the use of the immunogold labelling method, we have confirmed the Notch4 presence in the cytoplasm and nucleus of tumour cells." (PMID 37108670, 2023). "Together, these results suggest that the loss of Notch4 can lead to downregulated expression of Pcsk5 in PanIN and PDAC lesions, and may have contributed to the reduced tumor burdens and improved survival in the N4−/−PKC mice." (PMID 36970723, 2022). "Enhanced anti-tumor immunity was observed in NOTCH4-Mut tumors." (PMID 35967450, 2022). "Our findings suggest that a high expression of SOX8, Notch4, and Hes5 could lead to tumor metastasis." (PMID 36246971, 2022). "Gene set enrichment analysis revealed NOTCH4-Mut tumor enhanced anti-tumor immunity." (PMID 35967450, 2022).